YY1 (YY1 transcription factor)
Diseases named in the same sentence as YY1 in open-access papers (continued):
Sharing a sentence is not in itself a finding about the gene and the disease.
tumor (continued). "Studies have shown that YY1 expression is positively correlated with PD-L1 expression, so elevated YY1 expression is expected to be a molecular marker for diagnosing T cell-mediated tumor immune escape." (PMID 37081988, 2023). "The isorhamnetin and anti-PD-L1 antibody dual-functional nanoparticles can improve tumor immune microenvironment and inhibit YY1-mediated tumor progression." (PMID 37408047, 2023). "Our next point of attention was to decipher associations between YY1/PEBP1 methylation (beta values) and immune cell infiltrates, across different tumor types." (PMID 37894300, 2023). "Subsequently, virtual screening and cell-function assay were performed to screen the USP7 inhibitors for regulating YY1 expression and inhibiting tumor progression." (PMID 37408047, 2023). "Ideally, the inhibition of YY1 will lead to the sensitization of resistant tumor cells to drug-induced apoptosis and encourage tumor growth inhibition." (PMID 37686541, 2023). "This IL-2 downregulation is a large factor in the decline in cytotoxic function, as elevated YY1 levels were found in tumor-infiltrating lymphocytes." (PMID 37686541, 2023). "IHC staining was performed to detect the expression levels of USP7, YY1, E-cadherin, and vimentin in tumor tissues." (PMID 37408047, 2023). "Our results suggested that FOSL1, CEBPD, MXI1 and YY1 were critical TFs of tumor invasion induced by hypoxia, and they can be used as an independent prognostic signature to predict GBM survival." (PMID 37441593, 2023). "The current investigation showcases that the anomalous manifestation of YY1 stimulates the proliferation, migration, and invasion of PCa cells in vitro, and triggers the growth of tumours as well as metastasis to the lungs in vivo." (PMID 37771187, 2023). "We observed similar results in animal experiments, in YY1-depletion groups, tumor volume and weight were reduced after X-ray irradiation." (PMID 38065955, 2023). "Given that NEPC is a more aggressive type of PCa, our aim was to determine if YY1 is involved in tumour proliferation, invasion, and migration." (PMID 37771187, 2023). "The effect of tumor immunotherapy can be regulated by YY1, so we proposed a drug-development strategy that combined the regulation of YY1 expression with anti-PD-L1 monoclonal Ab." (PMID 37408047, 2023). "YY1 plays an important regulatory role in tumor cell EMT and tumor immune microenvironment formation." (PMID 37408047, 2023). "By analyzing the association between RBM14 expression and EP300 and YY1 levels using TIMER database, we found that RBM14 expression was strongly associated with the expression of EP300, CBP, and CTCF in various types of tumor tissues." (PMID 37060064, 2023). "YY1 also suppresses the expression of genes involved in the immune response and promotes immune evasion in tumor cells." (PMID 37444616, 2023). "Our subsequent objective was to determine the role of YY1 in regulating tumour metastasis through cellular migration, invasion and wound healing assays." (PMID 37771187, 2023). "As a tumor suppressor gene, the potential of YY1 as a valuable biomarker for the development of cancer had become increasingly known." (PMID 35359580, 2022). "The transcription factor YY1 is elevated in various types of cancers and promotes tumor growth and metastasis." (PMID 35811688, 2022). "Abnormal YY1 expression provides the driving force for tumor development by inhibiting fatty acid oxidation and promoting lipid accumulation." (PMID 36330745, 2022). "The higher expression pattern of YY1 transcription factor triggered the patients having larger tumor size, differentiation, higher TNM stage, and lymph node metastasis." (PMID 35632527, 2022).
tumor (continued). "YY1 has a dual function; it exerts tumor-promoting as well as -suppressive effects, depending on the cancer type." (PMID 36123703, 2022). "Both oncogenic and tumor suppressive roles of the transcription factor YY1 via regulation of cell proliferation and tumor metastasis have been reported." (PMID 36528654, 2022). "The results of cell biological function showed that YY1 promoted the proliferation and migration of tumor cells." (PMID 36626426, 2022). "YY2 mRNA was relatively low in tumor lesions compared to corresponding adjacent tissues; whereas YY1 and SLC7A11 mRNA was upregulated in tumor lesions." (PMID 35246964, 2022). "The results indicated that YY1 overexpression markedly promoted more tumor cells infiltration in adjacent fatty, nerve, and muscular tissues in contrast to that of the negative control vector groups." (PMID 35811688, 2022). "Hays and Bonavida found that there are several signal crosstalk pathways between YY1 and the expression regulation of immune cells and regulate the drug resistance of tumor cells to cellular immunotherapy through these pathways." (PMID 35359580, 2022). "O-GlcNAcylation can significantly regulate cells and important transcription factors in the tumor microenvironment, including the AhR, YY1, the NLRP3 inflammasome, MDSCs, NK cells, and CD8+ t cells, as well as sirtuins and core metabolic processes." (PMID 36613754, 2022). "Studies have found that YY1 is highly expressed in many cancers, participates in the regulation of tumor proliferation and growth, and plays a dual role in inhibiting or promoting tumor progression." (PMID 35359580, 2022). "In the paired and unpaired analysis, significant overexpression of YY1 was observed in tumor tissues compared with normal tissues and was associated with poor overall survival and disease specific survival." (PMID 36528654, 2022). "When tumor bulk reached 100 mm3, the xenograft tumors were injected with YY1 overexpression plasmids twice every week." (PMID 35811688, 2022). "The TCGA database was utilized to evaluate the expression of YY1 in various kinds of tumors using tumor immune estimation resource, version 2 (TIMER2)." (PMID 35791393, 2022). "Yin Yang 1 (YY1)-mediated DLEU1 boosted tumor growth, metastasis, epithelial-mesenchymal transition (EMT), stemness maintenance and drug resistance in vitro and in vivo." (PMID 35864972, 2022). "Future research should focus on the usefulness of nitric oxide and rituximab to decrease tumor angiogenesis, as those drugs can potentially inhibit YY1 expression." (PMID 35719931, 2022). "We selected 16 types of cancer data, among which YY1 expression level was most closely related to a variety of tumor-infiltrating immune cells." (PMID 35791393, 2022). "YY1 also fulfills important functions in cancer, where it can act either as a tumor promoter or tumor suppressor depending on the cancer type." (PMID 35693944, 2022). "Among them, IGF1R and EGFR can activate PI3K/AKT and MEK/ERK signaling pathways, respectively, to enhance tumor progression and drug resistance, and YY1 activates Wnt/β-catenin signaling by promoting CTNNB1 expression to promote tumor growth." (PMID 36131281, 2022). "Among YY1-repressed genes, many of them possess tumor-suppressive activities, including p21, p16INK4A, CEBPD, DR5, microRNA-29 and -206." (PMID 35406384, 2022). "Among them, GON4L is a transcriptional regulator gene that has been reported to drive tumor growth through the YY1-androgen receptor-CD24 pathway." (PMID 36120364, 2022). "In this study, we uncovered that miR-30e-5p acts as a tumor suppressor in HCC by regulating YY1 as an upstream regulator competing with GRSF1." (PMID 34998399, 2022). "This work used existing data to explore the possible function of YY1 in tumor, generating recommendations for future cancer research." (PMID 35791393, 2022).
tumor (continued). "Meanwhile, analysis of RNA-seq data from the GEO, TCGA, and CCLE databases demonstrated that DICER1 was significantly correlated with YY1 mRNA expression both in cancer tissue and tumor cell lines." (PMID 35183226, 2022). "YY1 can maintain the survival of tumor cells and promote adaptation of cells to tumor microenvironment by regulating numerous genes related to cell proliferation, cell cycle, and inflammatory response." (PMID 35265610, 2022). "Despite its tumor-promoting role, YY1 contributes to the reprogramming of tumor cell metabolism, to aid the cell’s adaption to different microenvironments." (PMID 36123703, 2022). "The research of YY1 in tumor has become more and more mature, but the specificity of its drug is still poor." (PMID 36626426, 2022). "circPTPRF knockdown reduced the tumor size and prolonged the survival time of mice, and the staining intensity of YY1 and ki-67 decreased." (PMID 36397164, 2022). "YY1 regulates genes related to the cell cycle, cell death, and tumor metabolism; YY1 is highly expressed in many cancers." (PMID 36230577, 2022). "In this review, we summarize the relevant mechanisms of the interaction between YY1 and noncoding RNAs during tumor progression, which will provide a possible theoretical basis for the clinical treatment of tumors." (PMID 36626426, 2022). "In another mechanism, YY1 can influence tumor angiogenesis by increasing the expression of angiopoietin factors ANG-1 and ANG-2, which are mediators of microvascular remodeling and capillary maturation." (PMID 35719931, 2022). "Many studies have confirmed that YY1 and lncRNAs have close and complex crosstalk, which play a crucial role in tumor progression." (PMID 36626426, 2022). "It is well known that YY1 is upregulated in various types of tumors and is crucial for tumor cell proliferation and metastasis." (PMID 35409160, 2022). "Transcription factor YY1 is an important regulator of many pathways in tumor cell growth, prognosis, epithelial-mesenchymal transition, invasion, and resistance to chemotherapy." (PMID 36626426, 2022). "So far, a great deal of evidence shows that YY1 played a key role in regulating the proliferation and development of tumor cells." (PMID 35359580, 2022). "From a functional point of view, YY1 overexpression rescued the tumor-inhibiting effect of decreased GRSF1 on HCC cell proliferation, apoptosis, colony formation and migration (p<0.05)." (PMID 34998399, 2022). "In the TCGA projects, we looked at the genetic alteration status of the YY1 gene in various tumor samples." (PMID 35791393, 2022). "YY1 has been reported to be abnormally expressed in a variety of tumors and is critical for tumor progression." (PMID 36424383, 2022). "Next, we injected those cells into the flanks of immunocompromised mice and after tumor establishment at around day 7, treated the animals for 4 weeks with doxycycline in the drinking water to stably knockdown YY1." (PMID 35693944, 2022). "Functionally, increased miR-30e-5p suppressed HCC cell colony formation, proliferation and migration, while YY1 overexpression counteracted the tumor-inhibiting effect induced by pre-miR-30e-5p (p<0.01)." (PMID 34998399, 2022). "The transcription factors YY1 and CP2 have been associated with tumor promotion and suppression in various cancers." (PMID 33315124, 2021). "The higher the expression of YY1 was, the better the tumor differentiation and the lower the tumor-node-metastasis (TNM) stage." (PMID 33985581, 2021). "Mounting evidence has indicated the presence of increased YY1 levels in various types of tumors and supported its crucial role for tumor cell proliferation and metastasis." (PMID 34497757, 2021). "The expression of miR-378c decreased and the expression of YY1 increased in cancer tissues and serum of tumour patients." (PMID 33794762, 2021). "The tumor-suppressive role found for both YY1 and BCL2L15/Bfk in CRC cells was further validated in patients, by analyzing relevant CRC datasets." (PMID 34445183, 2021).
tumor (continued). "In conclusion, our study uncovered the tumor-suppressive role of YY1 and BCL2L15, and their potential value as biomarkers useful in both diagnosis and prognosis of CRC patients." (PMID 34445183, 2021). "YY1 is a multifaceted factor in oncology and its function mostly depends on the molecular environment and specific tumor type." (PMID 34445183, 2021). "For example, YY1 cooperates with AP1 to induce the expression of tumor suppressing molecular chaperone HLJ1, thus reducing cell invasiveness of LUAD cells." (PMID 33758616, 2021). "The Yin Yang 1 (YY1) transcription factor is known to negatively regulate the expression of the Fas receptor and, thus, is implicated in tumor cell resistance to Fas-induced apoptosis." (PMID 34685635, 2021). "In vitro studies suggested a tumor-suppressive role for both YY1 and the hereby identified pro-apoptotic factor BCL2L15/Bfk, in two out of four CRC cell lines with different mutational genotypes." (PMID 34445183, 2021). "Accumulating evidence reveals that miR-449b-5p serves as a tumor suppressor by suppressing various cellular factors, such as yin and yang 1 (YY1), cell-cycle related and expression-elevated protein in tumor (CREPT), and Wnt family member 2B (WNT2B)." (PMID 34298879, 2021). "This further suggests that the inhibition of YY1 in tumor cells should lead to the inhibition of PD-1 expression in lymphocytes." (PMID 34944867, 2021). "YY1 promotes pancreatic clock progression and induces malignant changes, but YY1 seems to act as a tumor suppressor in PDAC and affects many biological behaviors, such as proliferation, migration, apoptosis and metastasis." (PMID 33985581, 2021). "Immunohistochemistry determined that YY1 was decreased in the tumours formed from circ‐LAMP1 depleted KMBC cells." (PMID 33675150, 2021). "Although the role of YY1 in gene regulation has been widely studied, the mechanism of YY1 action on tumour growth is distinct in different cancers." (PMID 33942988, 2021). "CRC dataset analyses corroborated a tumor-suppressive role for both YY1 and BCL2L15 whose expressions were inversely correlated with aggressiveness." (PMID 34445183, 2021). "We further confirmed that expression of YY1 was diminished in tumor tissues of the mice treated with sh-YY1." (PMID 34497757, 2021). "In cancer, in addition to the modulation of molecular processes similar to those in normal stem cells, YY1 governs the CSC phenotype via tumor-dependent molecular events." (PMID 33728560, 2021). "Several studies have shown that YY1 regulates biological functions of tumor cells by interacting with miRNAs or lncRNAs." (PMID 34485123, 2021). "Here, we found that overexpression of YY1 reversed the anti-tumor effect mediated by MIR31HG knockdown and that YY1 positively promoted MIR31HG expression." (PMID 34485123, 2021). "Inhibition of YY1 expression induced the migration and invasion of HCCs, which strongly suggested that YY1 acted as a tumour suppressor in HCCs." (PMID 32557953, 2020). "YY1 is highly expressed in metastatic tumor cells and is regarded as a bona fide inducer of cancer metastasis." (PMID 32226547, 2020). "YY1 results are conflicting, since this gene seems to act simultaneously as an oncogene and a tumour-suppressor in functional assays." (PMID 32429269, 2020). "Taken together, existing evidence suggests that YY1 regulation of tumor angiogenesis involves a complex, multi-pathway mechanism based on both direct and indirect activation of angiogenic genes, at the transcriptional as well as post-translational level." (PMID 32226547, 2020). "Taken together, our results showed that EC-specific YY1 deletion in mice significantly suppressed tumor growth." (PMID 33235311, 2020). "In conclusion, the present study demonstrates that YY1 acts as a tumour suppressor in the progression of HCC with a study of YY1 gain and loss of function." (PMID 32557953, 2020).
tumor (continued). "Previous reports have shown that tumor cells become refractory to TRAIL-mediated apoptosis upon downregulating DR5 via the transcriptional repressor yin yang 1 (YY1)." (PMID 35310881, 2020). "Together, these studies show the prominent role of YY1 in tumor cell proliferation and reveal the multiple regulatory mechanisms employed by YY1 at transcriptional, post-translational (e.g., protein modification and protein stability), and epigenetic level." (PMID 32226547, 2020). "To elucidate the cellular basis for the reduction of tumor growth and volume by endothelial-specific YY1 deletion, we focused on the neovascularization in tumor tissues." (PMID 33235311, 2020). "Studies have shown that transcription factor YY1 is overexpressed in most tumors and participates in regulating the resistance of tumor cells to cellular immunotherapy." (PMID 33344447, 2020). "Although there is abundant evidence to support the role of YY1 as a tumour promoter, recent reports have shown that YY1 also has a tumour inhibitory effect." (PMID 33221813, 2020). "In summary, our study shows that miR-548t-5p, which is regulated by YY1, is significantly downregulated in PC and suppresses tumor growth and metastasis by targeting CXCL11." (PMID 32341359, 2020). "The specified multifunctional role of YY1 in tumor angiogenesis points to YY1 being a good candidate to be targeted for cancer therapy." (PMID 33235311, 2020). "In vivo tumor xenograft model assays indicated that YY1 knockdown abolished USP21 overexpression-induced tumor growth." (PMID 31956270, 2020). "Studies have identified CNKN1A as a target gene of YY1 that binds to the BRCA2 protein to have a role in tumor suppression." (PMID 33232269, 2020). "YY1 in tumor cells enhances tumor angiogenesis by binding with the promotor of VEGFα and augmenting transcriptional activity in tumor cells." (PMID 33235311, 2020). "Recent studies have shown that YY1 is a critical regulator of tumor cell glucose metabolic reprogramming." (PMID 32226547, 2020). "Additional studies are required to further clarify the molecular pathways behind the specific effect of YY1 on gene expression in tumor ECs during tumor angiogenesis." (PMID 33235311, 2020). "YY1 can act either as an oncogene or a tumor suppressor depending on the cell context because of the multiple roles played by YY1 in regulation of transcription 22-24." (PMID 32929330, 2020). "How important is the O-GlcNAcylated YY1 suppression of Bmal1 to the function and circadian rhythm of tumour microenvironment cells?" (PMID 33375613, 2020). "Specifically, by using the tamoxifen induced EC-specific YY1 knockout mice, we showed that endothelial YY1 deletion significantly suppress tumor angiogenesis and tumor growth." (PMID 33235311, 2020). "In summary, this study uncovers the unique function of endothelial-specific YY1 in promoting tumor angiogenesis and tumor growth." (PMID 33235311, 2020). "An insight into the mechanism by which YY1 functions as a tumour promoter vs tumour repressor would help us design novel therapeutic approaches by targeting or manipulating the function of YY1." (PMID 32557953, 2020). "Here we report that the transcription factor Yin Yang 1 (YY1) in ECs is critically involved in tumor angiogenesis." (PMID 33235311, 2020). "To assess endothelial YY1 functional role in tumor angiogenesis, we initially determined the YY1 expression in tumor blood vessels of cancer tissue by immunohistochemistry." (PMID 33235311, 2020). "In this study, we have added substantial evidence supporting that endothelial YY1 has a critical role in promoting tumor angiogenesis and tumor growth." (PMID 33235311, 2020). "Intravenous injection of YY1-knocked-down A549 cells resulted in decreased tumor cells colonization in lung compared to control cells." (PMID 32226547, 2020). "YY1 plays a crucial role in HIF-1α-induced tumor angiogenesis by regulating HIF-1α at post-translational level." (PMID 32226547, 2020).